SST (somatostatin)
Diseases named in the same sentence as SST in open-access papers (continued):
Sharing a sentence is not in itself a finding about the gene and the disease.
diabetes (72 papers, 2008 to 2026). "Somatostatinomas produce excess somatostatin causing symptoms of diabetes, gallstones, diarrhea, and steatorrhea (fatty stools)." (PMID 40144450, 2025). "Results are divergent between species with respect to delta-cell mass in diabetes, as delta-cell hyperplasia was reported in adult Goto-Kakizaki diabetic rats associated with an increased expression of somatostatin." (PMID 38612880, 2024). "For example, the loss of Urocortin3 (Ucn3) from β-cells at early stages of diabetes deprive δ-cells of the principal stimulatory factor for somatostatin release." (PMID 33494193, 2021). "In diabetes, beta cell deficiency, together with alpha cell insulin and somatostatin resistance, all contribute to alpha cell dysfunction and a loss of the regulation of glucagon secretion, resulting in hyperglucagonemia." (PMID 34659118, 2021). "To mimic this increase in SST release in diabetes, we increased gGIRK in the mathematical model (increased SST release would cause hyperactivation of GIRK channels)." (PMID 27044683, 2016). "The hormone somatostatin inhibits growth hormone release from the pituitary gland and is theoretically linked to diabetes and diabetes related complications." (PMID 25880900, 2015). "While this review focuses on SST-dependent mechanisms of glucagon counterregulatory failure in insulin-deficient diabetes, other causative mechanisms, such as changes in the anatomical and paracrine relationships between α- and β-cells, may also play a role." (PMID 38298268, 2023). "Furthermore, it has been suggested that diabetes is associated with impaired somatostatin release and/or delta cell death." (PMID 31420552, 2019). "Gastritis caused by H. pylori may affect the secretion of gastric-related hormones, such as leptin and growth hormone-releasing hormone, as well as gastrin and somatostatin, which may affect the susceptibility to diabetes." (PMID 31583248, 2019). "Consistent with selective β cell ablation in STZ-diabetic pigs, insulin mRNA by RT-PCR was significantly decreased (p<0.0001), somatostatin and pancreatic polypeptide transcript levels were unaltered, while glucagon mRNA showed the characteristic increase associated with diabetes (p<0.0001)." (PMID 18320053, 2008). "This review synthesizes current knowledge on the secretion mechanisms of insulin, glucagon, somatostatin, ghrelin, and pancreatic polypeptides, emphasizing their functional crosstalk in diabetes." (PMID 40919135, 2025). "Excessive secretion of somatostatin produces a specific syndrome that includes steatorrhea, mild diabetes, and cholelithiasis." (PMID 40941664, 2025). "In PDAC donors with diabetes, INS positively correlated with both GCG and SST, suggesting a simultaneous loss of multiple endocrine cell types." (PMID 40244011, 2025). "For example, delta cell death as well as impaired somatostatin (SST) secretion were found in animal models of diabetes mellitus." (PMID 39493348, 2024). "Literature suggests that islet hormone secretion is regulated by glucose levels in the blood and decreased secretion during diabetes correlates with disrupted secretion of pancreatic hormones such as insulin, glucagon, and somatostatin." (PMID 38529398, 2024). "Conversely, the expression of the GHS-R was upregulated on beta-cells during diabetes, although the major paracrine action of ghrelin within the islet is considered to be on somatostatin release." (PMID 38612880, 2024). "Following the inhibition of insulin secretion by the increased serum values of somatostatin, patients with somatostatinoma can present hyperglycemic changes through glucose intolerance from modified fasting glucose to the onset of diabetes." (PMID 37628857, 2023). "As a result of these effects, the hypersecretion of somatostatin will lead to the development of diabetes, steatorrhea, gallstones (following the decrease in the contractility of the gallbladder) and malabsorption." (PMID 37628857, 2023).
diabetes (continued). "Single-cell islet transcriptomes revealed that SST gene expression is differentially regulated in T2D islets compared to non-diabetes islets." (PMID 36834860, 2023). "SST is a growth hormone inhibitory peptide which plays a prominent role in several pathological conditions, including inflammation, diabetes mellitus, Alzheimer’s, Parkinson’s, and acquired immunodeficiency syndrome." (PMID 35207439, 2022). "Specific deletion of islet β cell cilia not only impairs insulin secretion, but also affects glucagon and somatostatin secretion of proximal α and δ cells, leading to diabetes." (PMID 36552853, 2022). "In patients with T2DM, decreased muscle mass leads to deteriorated insulin sensitivity, aggravated diabetes, increased somatostatin secretion, abnormal bone metabolism, and reduced bone mass, and is associated with osteoporosis." (PMID 36337638, 2022). "Although the importance of somatostatin in both diabetes and pancreatic disease have been realized, its role in DEP settings has not been thoroughly studied." (PMID 33250773, 2020). "In this study, it was found that somatostatin secreted by enteric neurons has an important effect in hyperglycemic conditions induced by streptozotocin injection in the swine diabetes model." (PMID 31952333, 2020). "Accordingly, diabetes patients, with low insulin secretion, experience hyperglucagonemia although their somatostatin secretion is even upregulated." (PMID 32774668, 2020). "There is also some evidence to suggest that circulating somatostatin concentrations can be increased in diabetes mellitus ulcerative colitis and vascular dementia." (PMID 33391185, 2020). "The administration of somatostatin analogs to patients with type 1 diabetes mellitus has also been reported to reduce serum IGF-1 and urinary albumin." (PMID 31540583, 2019). "The administration of somatostatin analogs to patients with type 1 diabetes mellitus resulted in improvement of the GFR and kidney size." (PMID 31540583, 2019). "Impaired release of SST from δ cells results in compromised paracrine control of β-cell activities, contributing to the pathogenesis of diabetes mellitus." (PMID 29880854, 2018). "For example, disruption of CRHR2 signaling in pancreatic SST-producing cells has been shown to contribute to diabetes development." (PMID 29880854, 2018). "In turn, a significant diabetic etiology component is manifested in GK rats, which much more resembles secondary diabetes mellitus observed in somatostatinoma or states after treatment with somatostatin analogs." (PMID 26236746, 2015). "In summary, our study has revealed that glucagon-producing α-cells and somatostatin-producing δ-cells can rapidly regenerate following a single diabetes-inducing dose of STZ treatment in adult mice." (PMID 22586489, 2012). "Since most β-cells have been destroyed, somatostatin becomes the main paracrine inhibitor of the α-cell in diabetes." (PMID 22969729, 2012). "It is well known that the release of glucagon by the pancreas is inhibited by both insulin and somatostatin; and in diabetes, defects in the release of these islet paracrine hormones contribute to the perturbation of glucagon release from α-cells." (PMID 22969729, 2012). "The inherited expression of Isl-1/Pax-6/Nkx6.1/Somatostatin transcripts in h-ASCs, its ease in availability and autologous origin, make it an eminent candidate for cell replacement therapy in diabetes." (PMID 21687731, 2011). "Of the major islet hormones only expression of SST was not significantly reduced in diabetes-associated PDAC, although both Somatostatin Receptor 3 (SSTR3) and SSTR5 which allow paracrine signaling of somatostatin to surrounding α- and β-cells were decreased." (PMID 40244011, 2025). "Transcriptomic data indicated significant downregulation of islet hormone genes insulin (INS) and glucagon (GCG) but not somatostatin (SST) in PDAC-associated diabetes, consistent with a type 3c diabetes phenotype." (PMID 40244011, 2025).
diabetes (continued). "The somatostatin-labeled D-cell number increased significantly as diabetes was induced." (PMID 39337311, 2024). "As PP can inhibit somatostatin production from human islets, this might represent a secondary contributor to the hyperglucagonemia of diabetes." (PMID 38612880, 2024). "The intra-islet role of the delta-cells and the impact of dysregulated somatostatin secretion on the defective counter-regulatory alpha-cell glucagon response to hypoglycaemia in T1D are excellent examples of a potentially novel tool in diabetes control." (PMID 38612880, 2024). "UCN3 secretion is reduced early in pre-diabetes, with the associated loss of UCN3-stimulated somatostatin release at the delta-cell causing the loss of an important element of rapid paracrine hormone control (such as at the alpha-cells), which will contribute to glycemic instability." (PMID 38612880, 2024). "Presenting symptoms are secondary to the inhibitory effects of somatostatin, thus patients may present with cholelithiasis, diabetes, and/or steatorrhea." (PMID 37046665, 2023). "Thus, it is possible that defects in the regulation of somatostatin secretion from δ-cells contribute to the pathogenesis of diabetes." (PMID 33494193, 2021). "In case of NF1-associated somatostatin-related symptoms, management is not well defined and can include treatment of diabetes, cholecystectomy, and pancreatic enzyme supplementation." (PMID 34025587, 2021). "Additionally, hypersecretion of somatostatin can disable the counter-regulatory glucagon secretion during insulin-induced hypoglycemia in diabetes." (PMID 33494193, 2021). "In diabetes, circulating and pancreatic somatostatin, together with SST mRNA, are elevated." (PMID 34659118, 2021). "We hypothesized that that strategy of developing β cell therapy against diabetes might need to consider the importance of glucagon-producing and somatostatin-producing cells in 3D structure." (PMID 32081132, 2020). "Human stem cell-derived SC-β cells develop into islet-like clusters comprised of cells that contain mainly insulin and, to a lesser extent, glucagon and somatostatin, and thus provide a unique opportunity to study diabetes in a human-derived cell culture system resembling native human islets." (PMID 32093375, 2020). "Our findings suggest that agents that reduce somatostatin action (SSTR antagonists) or secretion (SGLT2 inhibitors) might be useful as adjuncts to insulin in diabetes therapy." (PMID 30635569, 2019). "Moreover, in human diabetic patients, infusion of somatostatin was reported to improve glycemic control by reducing the hyperglucagonemia, but it is not known to which extent somatostatin secretion is altered in diabetes." (PMID 39803760, 2025). "This review highlights the normal regulatory role of pancreatic somatostatin signaling in healthy islet function and how the inhibition of somatostatin receptor signaling in pancreatic α-cells may restore normal glucagon counterregulation in diabetes mellitus." (PMID 38298268, 2023). "Therefore, restoring appropriate δ-cell function or somatostatin secretion/signaling in diabetes could provide novel avenues for developing treatments to recover impaired islet function and improve glucose control in the disease." (PMID 33494193, 2021). "Thus, somatostatin may represent an attractive approach for treating post-pancreatectomy diabetes by reducing glucagon secretion and improving glucose tolerance." (PMID 33270148, 2021). "The expression patterns of SSTRs in islet cells are altered in type 2 diabetes mellitus (T2DM), with diminished levels of SSTR1 and SSTR4 in α-cells and SSTR1-4 in δ-cells, which could further contribute to impaired somatostatin paracrine regulation in diabetes." (PMID 33494193, 2021). "Thus, it is possible to restore/optimize islet function in diabetes targeting somatostatin signaling, which could open novel avenues for the development of effective diabetic treatments." (PMID 33494193, 2021).
diabetes (continued). "Furthermore, in our case, the occurrence of diabetes might have been either due tothe partial excision of the pancreas or due to the treatment with somatostatin analogues, which are known to reduce theinsulin levels secreted by the pancreatic cells." (PMID 27928440, 2016). "Thus, the increase in local somatostatin and release of somatostatin delivery to the pancreas may both play a role in diabetes." (PMID 22969729, 2012). "The Cp+/SST+ and GCG+/SST + bi-hormonal cells were reported in zebrafish models of diabetes, lineage tracing experiments in mice, and during beta cell differentiation from human stem cells." (PMID 38933536, 2024). "Ga = gastrin, Glu = glucagon, In = insulin, PP = polypeptide, SS = somatostatin, VIP = vasoactive intestinal peptide, DM = diabetes mellitus, RFA = radiofrequency ablation." (PMID 34118524, 2021). "In type 2 diabetes mellitus (T2DM), somatostatin lowers glucose concentrations by inhibiting glucagon secretion and abnormalities in the GH-IGF-1 axis have been associated with increased cardiovascular risk in T2DM." (PMID 25880900, 2015). "In young (4 wk old) diabetes-prone NOD mice, glucagon-, insulin- and somatostatin-positive cells comprised most of the islet area (84.9±1.8%)." (PMID 25101835, 2014). "Immunofluorescence microscopy was performed for insulin, glucagon, and somatostatin presence on paraffin-embedded sections of pancreata from 20 donors without diabetes aged between 11 days and 79 years of age." (PMID 39791735, 2025). "We found that bi-hormonal cells containing glucagon/insulin, insulin/somatostatin, or glucagon/somatostatin each represented around 2–3% of total islet endocrine cells in individuals without diabetes or other metabolic diseases." (PMID 39791735, 2025). "Thus, a better understanding of the complexities of somatostatin biology, starting with its receptor distribution and signal transduction in specific islet cell subsets, could help minimize adverse effects on glycemia and lead to more targeted treatment modalities for diabetes." (PMID 37660302, 2023). "As the present study also used a single dose of STZ to induce diabetes, it was believed that depressed secretion of pulsatile GH in the STZ-treated group was a result of decreased hypothalamic GHRH activity with increased somatostatin tone." (PMID 30297647, 2018). "At an early stage of diabetes (1 week), the normal glucagon-somatostatin rim was absent, and α- and δ-cells were found at the center of the islet." (PMID 23762878, 2013). "Given the potency of somatostatin in inhibiting glucagon and insulin secretion, it is not surprising that defects in δ-cell function and aberrant regulation of paracrine interactions play a fundamental role in the development of diabetes." (PMID 33494193, 2021). "Though altered islet localization of alpha and delta cells together with slightly higher islet somatostatin content has been demonstrated, extensive delta cell hyperplasia has not been reported in previous studies and its potential significance for diabetes development has not been discussed so far." (PMID 26236746, 2015). "One could hypothesize that in diabetes, in absence of the tonic effect of insulin, islet α-cells are oversensitive to insulin and are exposed to increased somatostatin." (PMID 22969729, 2012). "Moreover, although DLS may regulate somatostatin/insulin release by transplanted islets, it did not improve blood glucose levels, body weight, and glucose tolerance in a mouse model of diabetes that received islet transplantation." (PMID 34711885, 2021). "Thus, an alteration in the H+/somatostatin (SST) pathway, which is involved in thyroid regulation and gastrin and insulin secretion, may trigger not only achlorhydria but also hypothyroidism and diabetes." (PMID 34944008, 2021).
schizophrenia (65 papers, 2008 to 2026). A major psychotic disorder characterized by abnormalities in the perception or expression of reality. "We extended these findings by specifying more subtle subtypes of SST interneurons and by determining the probable cortical layers for these schizophrenia-associated SST interneuron subtypes (nos." (PMID 39833308, 2025). "VIP+ cell-mediated inhibition of SST+ cells was impaired in a mouse model carrying a human polymorphism in the α5 nicotinic receptor subunit, associated with nicotine addiction and schizophrenia." (PMID 39916937, 2024). "Our study revealed a strong association between the DEGs of PV and SST interneurons and pathways related to schizophrenia." (PMID 37545878, 2023). "In our analysis, functional connectivity changes in schizophrenia additionally implicated the areas showing a high density of somatostatin interneurons." (PMID 37848404, 2023). "Dysfunction of PV or SST interneurons has been implicated in the development of schizophrenia and temporal lobe epilepsy." (PMID 37545878, 2023). "Our data identify mGlu1 as a target to preferentially increase mPFC SST-IN activity, providing an alternative means to rescue deficient inhibitory transmission in patients with schizophrenia." (PMID 34731619, 2021). "Notwithstanding this, alterations in other interneurons, particularly somatostatin-positive interneurons, have also been associated with schizophrenia." (PMID 32382134, 2021). "Schizophrenia-associated SST mRNA elevations have been reported in both posterior and anterior regions in schizophrenia subjects." (PMID 34746116, 2021). "Interestingly, dysregulation of PFC SST expression is implicated in numerous psychiatric disorders, including depression, bipolar disorder, and schizophrenia." (PMID 40462921, 2025). "Loss of both PV+ and SST+ interneurons has also been reported in post-mortem hippocampus and neocortex of patients with schizophrenia." (PMID 34588960, 2021). "In addition, multiple candidate genes implicated in schizophrenia or other psychiatric disorders were detected, such as SST, NPY, SLC32A1, HINT1, RELN, and IFITM3." (PMID 29958387, 2018). "The cognitive deficits of schizophrenia appear to be associated with altered cortical GABA neurotransmission in the subsets of inhibitory neurons that express either parvalbumin (PV) or somatostatin (SST)." (PMID 22937123, 2012). "The primary objective was to determine the extent of changes in parvalbumin, somatostatin, calbindin, and calretinin interneurons across brain regions and cortical layers in schizophrenia compared to healthy controls." (PMID 40501558, 2025). "We selected immunohistochemistry and mRNA studies that examined parvalbumin, somatostatin, calbindin, and calretinin interneuron density or expression in schizophrenia patients." (PMID 40501558, 2025). "Decreased PFC SST expression and immunoreactivity is documented in depression, bipolar disorder, and schizophrenia, as well as in amygdala and hippocampus." (PMID 40462921, 2025). "The data strongly suggests that in schizophrenia only selective interneuron populations are affected, with alterations of somatostatin and parvalbumin neurons being the most convincing." (PMID 37131313, 2023). "Specifically, the analysis identified 29 DEGs between PV and SST interneurons that were involved in schizophrenia-related pathways." (PMID 37545878, 2023). "In terms of understanding reduced MMN in schizophrenia, this is an exciting finding as there is evidence from post‐mortem studies of schizophrenia brain tissue of reduced somatostatin activity." (PMID 38867817, 2023). "Decreased expression of SST has been documented in a number of brain disorders including Alzheimer’s disease (AD), Parkinson’s disease, depression and schizophrenia." (PMID 36225731, 2022). "Pathologically, SST is involved in multiple diseases, such as schizophrenia, Alzheimer’s disease, depression, and obesity." (PMID 35052772, 2022).